PDCD1LG2 (programmed cell death 1 ligand 2)
Diseases named in the same sentence as PDCD1LG2 in open-access papers (continued):
Sharing a sentence is not in itself a finding about the gene and the disease.
tumor (continued). "The results demonstrated a positive correlation between FANCD2 and immune checkpoints in most tumor tissues, including CTLA4, HAVCR2, LAG3, PDCD1, PDCD1LG2, SIGLEC15, TIGIT, and particularly CD274." (PMID 38443946, 2024). "Third, the correlation module results showed that DSN1 was related to some well-known tumor immune-related biomarkers, such as PDCD1, CD274, PDCD1LG2, and CTLA4." (PMID 39555702, 2024). "Differential expression of colorectal neoplasia expressed (CRNDE) is positively correlated with tumor immunity, as it can increase the expression of immune checkpoints such as CD274 (PDL1), PDCD1LG2 (PD-L2), CD86, and CD276." (PMID 38967893, 2024). "Wherein, in BLCA tumor, CSF1R (rho = 0.706), HAVCR2 (rho = 0.686), IL-10 (rho = 0.682), and PDCD1LG2 (rho = 0.753) showed the strongest positive correlation with FAP expression." (PMID 37166418, 2023). "Among the tumor cell lines, MDA-MB-231 presented the highest levels of CD274 (PD-L1) and PDCD1LG2 (PD-L2) expression compared to all cell lines (all p < 0.014)." (PMID 36901916, 2023). "Based on the data downloaded from The Cancer Genome Atlas (TCGA) database and Genotype-Tissue Expression (GTEx), significant overexpression of PDCD1LG2 and for HAVCR2 was noted within tumour tissue." (PMID 36768201, 2023). "All immune checkpoints were significantly different between the normal and tumor groups (P < 0.05), in which PDCD1, CTLA4, and HAVCR2 were highly expressed in tumor tissues, while CD274, LAG3, and PDCD1LG2 were highly expressed in normal tissues." (PMID 37872211, 2023). "Higher expression of CXCL13 and HEYL in tumor cell than normal cell was found, as well as the lower expression of ANKRD35 and PDCD1LG2." (PMID 37397391, 2023). "With RNA‐sequencing, IL‐1β enhanced a range of immune inhibitory molecules expression on tumor cells, including CD274, PDCD1LG2, and IDO1." (PMID 37009412, 2023). "The expression of HAVCR2, PDCD1LG2 and SIGLEC15 is prominently different in normal and tumor samples." (PMID 37065485, 2023). "SIGLEC15, PDCD1LG2(PD-L2), TIGIT, PDCD1(PD-1), CD274(PD-L1), CTLA4, LAG3, and HAVCR2(TIM3) are immunological checkpoints that perform a vital function in tumor immune evasion." (PMID 35840882, 2022). "Expression analysis revealed that HPV integration disrupted gene expression, but the upregulation of CD274, PDCD1LG2, FOXA1, and TNFSF4 provided opportunities for tumor immunotherapy." (PMID 35392231, 2022). "Finally, enrichment analysis confirmed that CD274 and PDCD1LG2 were associated with numerous biological pathways, such as: “Activation of Immune Reactions” and “Epithelial-Mesenchymal Transition,” suggesting that CD274 and PDCD1LG2 play crucial roles in cancer immunity and tumor metastasis." (PMID 36276934, 2022). "Among them, TGFB1 and VEGFA are tumor-secreted immunosuppressive factors, while CD274 (PDL1) and PDCD1LG2 are both PD1 ligands and cell-surface immunosuppressive factors." (PMID 35222383, 2022). "SIGLEC15, PDCD1LG2 (PD-L2), TIGIT, PDCD1 (PD-1), HAVCR2 (TIM3), CTLA4, LAG3, and CD274 (PD-L1) are transcripts related to immunological checkpoints that have a function in tumor immune evasion." (PMID 36042287, 2022). "CTLA4, HAVCR2, PVRL2, PDCD1, SIGLEC15, TIGIT, and VTCN1 expression levels were higher in tumor tissues, while CD244, LAG3, PDCD1LG2, and CD274 expression levels were found to be lower." (PMID 35923695, 2022). "Expressions of CD274, CTLA4, LAG3, PDCD1, PDCD1LG2, and SIGLEC15 were shown to be significantly different between normal and tumor samples in immune checkpoint analysis." (PMID 36588699, 2022). "At the same time, in order to investigate the relationship between type and immune checkpoints, we selected genes related to tumor immune checkpoints: PD-L1, CTLA4, LAG3, PDCD1, PDCD1LG2, and TIGIT." (PMID 36105091, 2022). "The results showed that CTLA4, HAVCR2, PDCD1, PDCD1LG2, and TIGIT significantly differed in tumor tissues and normal tissues." (PMID 36618928, 2022).
tumor (continued). "The expression of CD274, CTLA4, LAG3, PDCD1, PDCD1LG2 and SIGLEC15 was significantly different between adjacent normal tissues and tumor tissues." (PMID 36588699, 2022). "The results indicated that CD274/PDCD1LG2 expression was positively correlated with stromal, immune, and ESTIMATE scores but negatively correlated with tumor purity." (PMID 36276934, 2022). "TGFBR1, PDCD1LG2, CD274, and TNFSF14 are involved in tumor immune evasion and are effective targets for tumor immunotherapy." (PMID 36371223, 2022). "Important immunological checkpoints involved in tumor immune escape include CD274, IL1B, IL1A, PDCD1, PDCD1LG2, and SIRPA." (PMID 35401746, 2022). "In the benign urothelial lesions we also detected PDCD1LG2 expression by qPCR in all samples tested, and the levels of expression were similar to those found in the NMIBC tumor samples." (PMID 33718196, 2021). "The expression of certain immune checkpoints (such as PDCD1LG2, HAVCR2, CD276, and IDO1) also played an important role in the regulation of immune response by inhibiting the activation of anti-tumor immunocytes and inducing immune escape." (PMID 34490033, 2021). "Eight tumor-related immunosuppressive molecules, CD274, CTLA4, HAVCR2, LAG3, PDCD1 (PD1), PDCD1LG2, SIGLEC15, and TIGIT, had higher expression in HNSCC tumor tissues compared with HNSCC normal tissues." (PMID 34917682, 2021). "CAFs induce depletion and dysfunction of tumor-specific T cells by antigen cross-presentation and cellular interactions mediated by Fas ligand (FASL) and programmed cell death 1 ligand 2 (PD-L2)." (PMID 34681633, 2021). "Her tumor was also positive for Sig3, and OncoPanel sequencing revealed high-level genomic amplifications in CD274 (PD-L1) and PDCD1LG2 (PD-L2), which were confirmed by FISH." (PMID 32193378, 2020). "Cell line screening showed the enrichment of cancer cells deprived of the expression of CD27, CEACAM1, CTLA4, LRIG1, PDCD1LG2, or TNFRSF18, suggesting their role as tumor suppressor." (PMID 31358815, 2019). "The PD-1 receptor on T cells interacts with PD-1 ligands including PD-L1 (CD274) and PD-L2 (PDCD1LG2), on the surface of tumor cells." (PMID 31075138, 2019). "FFPE sections were macrodissected to enrich for tumor for quantitative assessment of CD274 (PD-L1), PDCD1LG2 (PD-L2), CD8A, and IRF1 by RT-qPCR multiplex mRNA panel." (PMID 31533832, 2019). "It was suggested that tumor-related genes such as NNMT, FLI1, GAS6, IncRNA CCAT1, PDCD1LG2, and CD274 are key regulators in tumor-like transformation under long-time exposure to P. gingivalis." (PMID 30671195, 2019). "Within the inflammation-tumor microenvironment, CD274 and PDCD1LG2 play an important role in facilitating immune escape for tumor cells." (PMID 28286742, 2017). "With the facilitation of bioinformatics analyses and validation, we identified some tumor-related genes, such as NNMT, FLI1, GAS6, lncRNA CCAT1, PDCD1LG2, and CD274, as the key regulators in the present tumor-like transformation model." (PMID 28286742, 2017). "There was concurrent and significantly increased expression of the immune checkpoint pathway markers HAVCR2 (TIM-3), CTLA-4, PDCD1 (PD-1), PDCD1LG2 (PD-L1), LAG3, and TIGIT, demonstrating increased immune suppressive signaling from both the tumor and immune cell populations." (PMID 38418892, 2025). "Additionally, PDCD1LG2 is associated with T cell exhaustion, and its modulation by TCF-1 indicates that overexpression may delay the onset of exhaustion, thereby extending the functional lifespan of CAR-T cells and enhancing their sustained anti-tumor activity." (PMID 41293181, 2025). "The high-response group exhibited elevated expressions of BTLA, LGALS9, PDCD1LG2, TIGIT, TNFSF15, and VTCN1 compared to the low-response group, suggesting that patients with this tumor profile may benefit from ICIs therapy." (PMID 40761787, 2025).
tumor (continued). "Importantly, the authors also demonstrated that tumour-related genes, such as NNMT, FLI1, GAS6, lncRNA CCAT1, PDCD1LG2, and CD274, were key regulators of neoplastic transformation in response to a low multiplicity of oral pathogen infection." (PMID 41228271, 2025). "In our study, we found that high PSMB2 expression may induce the upregulation of CD274, CTLA4, HAVCR2, LAG3, PDCD1, PDCD1LG2 and SIGLEC15, which are molecules on immune cells that facilitate tumor immune escape." (PMID 38467767, 2024). "We hypothesize that intrinsic expression of CTLA-4, PDCD1 (PD1), CD274 (PD-L1), PDCD1LG2 (PD-L2), CD276 (B7-H3), JAK2, and FoXO1 in neoplastic cells depends on BC immunophenotype, stem cell properties, and tumor microenvironment." (PMID 36901916, 2023). "Moreover, risk scores were negatively related to the expression of CD274, CTLA4, ICOS, LAG3, PDCD1, and PDCD1LG2 and negatively correlated with CD8+, CD4+, and Treg tumor-infiltrating immune cells." (PMID 37674251, 2023). "Additionally, the analysis of the CGGA and TCGA databases also showed that CDCA7 was closely related to several tumor-related suppressors, including CD80, CD276, CD28, PDCD1LG2, and TNFSF4, which contribute to tumor development via multiple mechanisms." (PMID 37510310, 2023). "Within the TME, cDCs have been shown to acquire a common gene program characterized by the expression of immunoregulatory genes (e.g., CD274/PD-L1, PDCD1LG2/PD-L2 and CD200), LAMP3 and CCR7, thus informing the naming of these tumor-specific cells mregDCs or LAMP3+CCR7+ cDCs." (PMID 36949244, 2023). "The B7 immune checkpoint superfamily includes B7-1 (CD80), B7-2 (CD86), B7-H1 (PD-L1, CD274), PD-L2 (PDCD1LG2), B7-H3 (CD276), B7-H4 (B7-x, VTCN1), and the inducible costimulator ligand (L-ICOS, CD275), which act as ligands on the surface of tumor cells or antigen-presenting cells." (PMID 36983005, 2023). "Interestingly, OSCC with high F3 expressed higher levels of the key immune checkpoint molecules CD274/PD-L1, PDCD1LG2/PD-L2 and CD80, especially in tumor dendritic cells." (PMID 35053621, 2022). "Additionally, according to an analysis of the molecular profiling of circulating tumor cells (CTCs) and clinical factors in HNSCC, it was found that the expression of PDCD1LG2 as PD-1 ligand genes was related to poor prognosis of HNSCC." (PMID 36671475, 2022). "SIGLEC15, PDCD1LG2(PD-L2), TIGIT, PDCD1(PD-1), CD274(PD-L1), CTLA4, LAG3, and HAVCR2(TIM3) are transcripts related to immunological checkpoints that perform vital functions in tumor immune evasion." (PMID 36253777, 2022). "To comprehensively inspect the immune microenvironment of HCC TME, we firstly compared gene expression of immune inhibitory checkpoint molecules between tumor tissues and normal (peri-tumor) tissues, including CD274, CTLA4, HAVCR2, LAG3, PDCD1, PDCD1LG2, TIGIT, and SIGLEC15." (PMID 35444645, 2022). "SIGLEC15, PDCD1LG2 (PD-L2), TIGIT, PDCD1 (PD-1), CD274 (PD-L1), CTLA4, LAG3, and HAVCR2 (TIM3) are transcripts related to immunological checkpoints that perform a vital function in tumor immune evasion." (PMID 36042287, 2022). "Our research mainly assessed the heterogeneity of tumor-infiltrating immune cells in OV TME and found that three immune checkpoint genes CD274, CTLA-4, and PDCD1LG2, showed negative correlations with risk scores." (PMID 35137909, 2022). "Therefore, we evaluated the relationship between the expression of immune inhibitory molecules (TIGIT, PDCD1LG2, PDCD1, LAG3, HAVCR2, CTLA4, and CD274) in the immune ignorant, immune inactive, and hot tumor subtypes." (PMID 33777927, 2021). "Concerning prototypical immune checkpoints, expression of CD274 (PDL1) and PDCD1LG2 (PDL2), which encode ligands for PDCD1 (PD1), expressed in tumor-infiltrating T cells, was virtually absent in the profiled human GBM tumors." (PMID 34917090, 2021). "PANX1 may promote tumor progression and immune suppression by co-expression of immunoinhibitors, such as CD274, PDCD1LG2, and TGFBR." (PMID 34796785, 2021).
tumor (continued). "Tumor samples of Inserm series were predicted in 2 and 4 subtypes molecular classification using a predictor based on nine genes: ADAM19, ETS1, and PDCD1LG2 for C1 and C2; CLDN1, DSC3, and SLC24A3 for C1A and C1B; CHL1, ECM2, and PTPN13 for C2A and C2B subtype prediction." (PMID 32083805, 2020). "However, immune checkpoint genes including IDO1, HAVCR2, PDCD1LG2, CD274, CTLA4, and TIGIT were significantly up-regulated in tumor samples (fold change >1.30, FDR q ≤ 1.0e-5)." (PMID 33257699, 2020). "Thus, JAK2 deletion is a potential mechanism to hide tumor cells from recognition by cytotoxic T cells, especially in the cases of CDC274 and PDCD1LG2 deletions." (PMID 28977839, 2017). "Taken together, NNMT, FLI1, GAS6, lncRNA CCAT1, PDCD1LG2, and CD274, whose differential expression was confirmed, may be involved in the major mechanism of tumor-like transformation induced by chronic P. gingivalis infection." (PMID 28286742, 2017). "In the TRAP cohort study of 83 oesophageal adenocarcinoma biopsies, the HER2-positive tumours were enriched for epithelial markers (EPCAM, E-cadherin), but exhibited lower immune cell infiltration (CD8+ T-cells, NK cells) and reduced expression of immune exhaustion markers (PDCD1LG2, CTLA4)." (PMID 41463236, 2025). "Furthermore, KIF18A expression was positively correlated with many common immune checkpoints, including PD-L1, PD-1, CTLA4, TIGIT, HAVCR2, PDCD1LG2, and LAG3, indicating that KIF18A may be a new target for tumor immunotherapy." (PMID 36830695, 2023). "Furthermore, defective expression of MHC molecules may lead to tumor immune evasion or resistance to ICB therapy, we found that CD274 and PDCD1LG2 were globally correlated with several immunosuppressive molecules, MHC molecules, and chemokines across cancers." (PMID 36276934, 2022). "In addition, the expression of PTBP3 was positively correlated with the expression of immune checkpoints PDCD1LG2 in most tumours, while a negative correlation was only found in THYM tumours." (PMID 35359851, 2022). "However, alterations in this pathway were consistently high regardless of changes in tumor purity, and PDCD1LG2 and PDCD1 expression." (PMID 34100771, 2021). "There is evidence that T cells lose their effector function and ability to kill tumor cells when stimulated by tumor antigens, which may be due to the increasing diversity and number of inhibitory receptors, including CD274, PDCD1LG2, HAVCR2, CTLA4, LAG3, PDCD1, TIGIT." (PMID 33592580, 2021). "Thus, tumor cells may express CD80/86 to suppress T cell activity via binding to CTLA4, or express PD-1 ligands PD-L1 (CD274) or PD-L2 (PDCD1LG2, PD-2 ligand)." (PMID 32903482, 2020). "In addition, this study suggested that PDCD1LG2 (PD-L2) and TNFRSF18 could be the suppressor of tumor cells." (PMID 31358815, 2019). "Deletions of PD-L1 (CD274) and PD-L2 (PDCD1LG2) genes were always accompanied by JAK2 deletion, suggesting that JAK2 deletion may be a mechanism to safeguard tumor cells from activated cytotoxic T cells in the absence of negative regulators PD-L1/PD-L2." (PMID 28977839, 2017). "In combining results of bioinformatics analyses and validation assays, tumor-related genes such as NNMT, FLI1, GAS6, lncRNA CCAT1, PDCD1LG2, and CD274 may be considered as the key regulators in tumor-like transformation in response to long-time exposure of P. gingivalis." (PMID 28286742, 2017). "We observed a high concordance with immune cell-related but not tumor cell-related genes (NGFR, MITF, MLANA, SLC45A2) and correlation with expression of PDCD1LG2 and SUSD3, irrespective of the side of metastasis." (PMID 38386085, 2024). "In 27 of 33 tumours, the expression of PTBP3 was positively correlated with the expression of immune checkpoints PDCD1LG2, while a negative correlation was found in the tumour of THYM." (PMID 35359851, 2022).
tumor (continued). "We used qPCR to analyze the ALDH3A2, PDCD1, PDCD1LG2, and CTLA-4 mRNA expression levels in 52 tumor tissues, which indicated a negative spatial correlation between ALDH3A2 and PDCD1 (R2 = 0.3576), PDCD1LG2 (R2 = 0.3878), and CTLA-4 (R2 = 0.2556)." (PMID 33148208, 2020). "Interestingly, PD-1 (gene symbol, PDCD1) and PD-L2 (gene symbol, PDCD1LG2), but not PD-L1 (gene symbol, CD274), are included in this global immune gene signature, likely because PD-L1 was expressed in intraepithelial immune cells, but not in tumor cells." (PMID 30956779, 2019).